WNT3 (Wnt family member 3)
Diseases named in the same sentence as WNT3 in open-access papers (continued):
Sharing a sentence is not in itself a finding about the gene and the disease.
chronic lymphocytic leukemia (4 papers, 2020 to 2023). "Wnt members, including Wnt3, Wnt4, Wnt5B, Wnt6, Wnt7B, Wnt9A, Wnt10A, Wnt14 and Wnt16, are highly expressed in chronic lymphocytic leukaemia B cells." (PMID 33417298, 2021). "It has been shown that in B-cells of Chronic Lymphocytic Leukemia (CLL), mRNA related to Wnt elements is overexpressed, such as WNT3, WNT5B, WNT6, WNT10A, WNT14, WNT16 or FZD3." (PMID 37237497, 2023). "WNT3 and WNT16 specifically increased in chronic lymphocytic leukemia (CLL), indicating the specificity of WNTs in leukemia." (PMID 35850748, 2022).
depression (4 papers, 2015 to 2024). "In previous GWAS and clinical studies, these genes have been associated with neurogenesis (WNT3), neurodevelopmental delays (QRICH1), addiction (HCG27), depression (CCDC71, CYP21A2), and other brain-related disorders." (PMID 39269986, 2024). "The selective reduction of Wnt3 expression in the ventral hippocampus following chronic restraint stress (CRS) suggested that Wnt3 plays some roles in CRS-induced depression-like behaviors." (PMID 37426090, 2023). "Second, we found that Wnt2 or Wnt3 was sufficient for buffering CRS-induced depression-like behaviors." (PMID 27622936, 2016). "Knocking down Wnt2 or Wnt3 in the VH led to impaired Wnt/β-catenin signaling, neurogenesis deficits and depression-like behaviors." (PMID 27622936, 2016). "Taken together, our study indicates essential roles for Wnt2 and Wnt3 in CRS-induced depression-like behaviors and antidepressant." (PMID 27622936, 2016). "Taken together, our results demonstrated that Wnt2 or Wnt3 in the VH is necessary and sufficient for alleviating depression-like behaviors." (PMID 27622936, 2016). "Our results suggested that the effects of overexpressing Wnt2 and Wnt3 more specifically resulted in a reversal of stress-induced depression-like behaviors." (PMID 27622936, 2016). "Our above experiments showed that CRS induces a synchronous reduction in Wnt2 and Wnt3, and that Wnt2 and Wnt3 participate in depression-like behaviors." (PMID 27622936, 2016). "Our results showed that CRS could selectively decrease the expression of Wnt2 and Wnt3, so we next investigated whether endogenous Wnt2 and Wnt3 are functionally related to depression-like behaviors." (PMID 27622936, 2016). "We next tested whether overexpressing Wnt2 or Wnt3 in the VH is sufficient for alleviating CRS-induced depression-like behaviors." (PMID 27622936, 2016). "In contrast, overexpression of Wnt2 or Wnt3 reversed CRS-induced depression-like behaviors." (PMID 27622936, 2016). "The selective reduction of Wnt2 and Wnt3 expression in the VH following CRS suggested that Wnt2 and Wnt3 may play roles in CRS-induced depression-like behaviors." (PMID 27622936, 2016). "Importantly, the screening of small molecule compounds to increase levels of Wnt2 or Wnt3 could be a method for identifying potential new targets for interventions for depression." (PMID 27622936, 2016). "Our results demonstrated that overexpressing Wnt2 or Wnt3 was sufficient for alleviating CRS-induced depression-like, but not anxiety-like behaviors." (PMID 27622936, 2016). "Together, our results suggested that knockdown of Wnt2 or Wnt3 expression in the VH could mimic CRS-induced depression-like, but not anxiety-like behaviors." (PMID 27622936, 2016). "Moreover, we found that knockdown of Wnt2 or Wnt3 could mimic the depression- but not anxiety-like behaviors." (PMID 27622936, 2016).
endometrial carcinoma (4 papers, 1997 to 2023). A malignant tumor arising from the epithelium that lines the cavity of the uterine body. "The WNT4 mRNA level was lower while WNT2, WNT3, and WNT5A mRNA levels were higher in endometrial carcinoma in comparison to normal endometrium." (PMID 26366420, 2015). "Also WNT2, WNT3, WNT4, and WNT5A genes expression was higher in normal human primary epithelial and stromal endometrial cultures compared to endometrial carcinoma cell lines, what suggest their participation in endometrial neoplasia." (PMID 26366420, 2015). "In contrast, not upregulation but downregulation of WNT-4, WNT-2, WNT-3, and WNT-5A was found to be important for endometrial cancer development." (PMID 37176048, 2023). "In contrast, in four endometrial carcinoma cell lines (RL95-2, HEC-1-A, AN3 CA and Ishikawa), Wnt2 and Wnt3 mRNAs were absent." (PMID 9099960, 1997).
gastric tumors (4 papers, 2015 to 2022). "Furthermore, the Wnt receptor Fzd7, which can bind Wnt3, transmits oncogenic Wnt signalling to drive the proliferation of gastric tumours in vivo." (PMID 36040316, 2022). "Previous studies found that the Wnt3 overexpression activates the Wnt/β-catenin pathway and overexpression of the Frizzled-7 corresponds to the activation of the canonical Wnt pathway in the esophageal and gastric tumors." (PMID 26498690, 2015). "However, how lipid-modified Wnt3 is disseminated in gastric tumour tissues is unclear." (PMID 36040316, 2022).
intestinal tumor (4 papers, 2021 to 2023). "LAT1 affects intestinal tumor development in a cell-extrinsic manner through reduced Wnt3 expression in Paneth cells." (PMID 36739585, 2023). "Paneth cells, known for their production of antimicrobial peptides and growth factors in the gut epithelium, are found to play a key role in intestinal tumor formation through secretion of Wnt3." (PMID 33372038, 2021).
leukemia (4 papers, 2008 to 2022). A malignant (clonal) hematologic disorder, involving hematopoietic stem cells and characterized by the presence of primitive or atypical myeloid or lymphoid cells in the bone marrow and the blood. "And the opposite effects of WNT3 in solid tumors and leukemia accentuated the complexity of WNT signaling in tumors." (PMID 35850748, 2022). "Six genes were identified in baboons (WNT3, POU2AF1, CCR7, ARG2, CD177, and WLS) and validated in human leukemia patients exposed to radiotherapy." (PMID 33737626, 2021). "In contrast, we have previously shown that ATL patient-derived leukemia cells activate the non-canonical Wnt pathway and over express Wnt5 but do not present activation of β-catenin or Wnt3." (PMID 28920078, 2017).
oral cancer (4 papers, 2020 to 2024). "As such, we propose that the regulatory mechanisms of the EMT pathway related to Wnt-3/β-catenin and p65 played a critical role in the development of oral cancer and thus in the inhibition caused by chrysophanol." (PMID 33014112, 2020). "Our previous study showed that chrysophanol ameliorated EMT in oral cancer cells through a Wnt-3-dependent pathway and also regulated oral cancer cell death, ROS production, and metastasis." (PMID 34063134, 2021). "Our pharmacological findings support Wnt-3 as a therapeutic target in oral cancer development and metastasis." (PMID 33014112, 2020). "Therefore, we speculated that the WNT3 and WNT pathway might be associated with resistance to 5FU in oral cancer." (PMID 38711026, 2024). "Thus, the aim of this study is to speculate on the role of chrysophanol in EMT in oral cancer cell lines via the Wnt-3 signaling pathway." (PMID 33014112, 2020).
Parkinson disease (4 papers, 2013 to 2022). A progressive degenerative disorder of the central nervous system characterized by loss of dopamine producing neurons in the substantia nigra and the presence of Lewy bodies in the substantia nigra and locus coeruleus. "Meanwhile, six genes near MAPT in chromosome 17 including MAPT-AS1, SPPL2C, CRHR1, KANSL1, NSF, and WNT3 have been identified as risk genes by earlier GWAS for Parkinson’s disease, another common neurodegenerative disorder which might present clinical symptoms of FTD." (PMID 35509074, 2022). "These included microtubule-related MAP2 and MAPT, as well as WNT3 and MICB, all implicated in the pathogenesis of diseases such as Parkinson’s, Alzheimer’s and schizophrenia." (PMID 31504236, 2019). "Variation in this region has been associated with Parkinson's disease (MAPT, PLEKHM1, NSF, c17orf69) progressive supranuclear palsy (MAPT), celiac disease (WNT3), bone mineral density (CRHR1) (NHGRI GWAS catalog) and intracranial volume." (PMID 23544013, 2013).
tetra-amelia syndrome (4 papers, 2017 to 2025). "To date, biallelic loss-of-function mutations in two genes have been reported to be causally associated with human tetra-amelia syndrome, WNT3 and RSPO2." (PMID 40723430, 2025). "Deficient WNT3 is associated with tetra-amelia syndrome, a Mendelian disease characterized by an absence of all limbs." (PMID 29566699, 2018). "A human genetic syndrome that is characterized by the absence of all four limbs (Tetra-amelia syndrome) results from the autosomal recessive inactivation of the WNT3 gene." (PMID 28347990, 2017).
adenoma (3 papers, 2021 to 2022). A neoplasm arising from the epithelium. "Our data confirm that in a genetic tumor model, PC-derived Wnt3 production is indeed important for tumor multiplicity, probably by sustaining early stages of adenoma formation in vivo." (PMID 33372038, 2021). "To address the possible contribution of PC production of Wnt3 to adenoma formation, we developed a PC-specific Wnt3 knockout mouse." (PMID 33372038, 2021). "PC depletion in ApcMin mice impaired adenoma development in the small intestine and led to decreased Wnt3 expression in small bowel adenomas." (PMID 33372038, 2021). "The requirement for PC-derived Wnt3 to support adenoma growth was further examined using organoid culture systems." (PMID 33372038, 2021). "Because both PCs and telocytes are known to express Wnt3 in the normal intestinal mucosa, the reduced expression seen in adenomas indicated that cells of PC lineage contribute the bulk of Wnt3 expression in the context of small intestinal adenomas." (PMID 33372038, 2021). "We propose that enhanced Wnt3 expression and an increase of cytonemes lead to augmented Wnt3 dissemination and signalling within GC cells, as well as increased cell proliferation and activity of cancer stem cells—a prerequisite for adenoma formation." (PMID 36040316, 2022). "This latter result indicates that the frequency of tumor stem cells in each adenoma, which are the organoid-initiating cells, is not affected by Wnt3 deficiency." (PMID 33372038, 2021). "Finally, we confirmed by RT-qPCR that our targeting strategy led to reduced Wnt3 expression in small intestinal adenomas." (PMID 33372038, 2021). "Furthermore, RT-qPCR analysis for 19 members of the Wnt family indicated that only two family members, Wnt3 and Wnt4, had reduced expression in adenomas from PCdel mice." (PMID 33372038, 2021). "Furthermore, the finding that PC-derived Wnt3 supports adenoma formation challenges the notion that intestinal adenomas are completely Wnt-independent." (PMID 33372038, 2021). "Thus, we speculate that upon reduction of Wnt3 in the tumor microenvironment, slow-growing small adenomas probably involute, much like the behavior of small adenomas in humans." (PMID 33372038, 2021). "Wnt3 is not essential for ligand-independent intestinal adenomas but is essential for Rnf43;Znrf3-mutant adenomas." (PMID 34788095, 2021). "Specifically, PC-specific Wnt3 deletion in mice resulted in lower adenoma burden but no change in adenoma size, yet in organoids derived from these adenomas we observed changes in growth rate but not in the amount of organoids derived per cells plated." (PMID 33372038, 2021).
cognitive deficit (3 papers, 2015 to 2025). "Despite these advances, the mechanisms by which peripheral nerve injury disrupts IGF‐1 and WNT3 signaling in the DG—and how such disruptions contribute to comorbid pain and cognitive impairment—remain poorly understood." (PMID 41414737, 2025). "WNT3 is a Wnt-signaling gene involved in neurogenesis, as well as in behavioral and cognitive deficits." (PMID 37709755, 2023). "Because Wnt3-induced NeuroD1 is a critical factor for neurogenesis and pancreatic development, it is suggested that the cognitive deficit and impairment of insulin secretion in diabetes, AD, and HD are due to the impairment of Wnt3-induced NeruoD1 activity." (PMID 26075247, 2015). "In the present study, we hypothesized that peripheral nerve injury induces comorbid neuropathic pain and cognitive impairment by disrupting the WNT3/IGF‐1 axis in the dorsal DG." (PMID 41414737, 2025). "We further tested whether targeted restoration of IGF‐1 or WNT3 function in the dorsal DG could reverse pain sensitization and cognitive deficits and explored the mechanistic interplay between these pathways." (PMID 41414737, 2025). "Similarly, chemogenetic activation of dorsal DG astrocytes alleviated comorbid symptoms by enhancing WNT3 secretion, while chronic inhibition of these astrocytes mimicked SNI‐induced pain hypersensitivity, cognitive impairment, and disrupted neurogenesis." (PMID 41414737, 2025).
glioma (3 papers, 2019 to 2024). A benign or malignant brain and spinal cord tumor that arises from glial cells (astrocytes, oligodendrocytes, ependymal cells). "In the present study, we also revealed that increased mRNA expressions of WNT16 was associated with shorter OS in patients with glioma, while the increased mRNA expressions of WNT3 and WNT5B were associated with longer OS." (PMID 32181818, 2020). "Conversely, the increased mRNA expression levels of WNT3, WNT5B and WNT10B were correlated with better OS in patients with glioma." (PMID 32181818, 2020). "Expanding our analyses to glioma samples in TCGA, we observed significant negative correlations for SALL2, WNT3, and SEMA5B with METTL7B expression." (PMID 38848215, 2024).
Hypertension (3 papers, 2019 to 2021). The presence of chronic increased pressure in the systemic arterial system. "Many Genome Wide Association Studies (GWAS) suggest the association between hypertension and WNT3 that encodes a canonical WNT ligand and SOX proteins which interact with b-catenin and modulate the transcription of WNT-target genes." (PMID 31822265, 2019). "Although numerous ncRNAs were shown to regulate WNT/β-catenin signaling in various cell types, and a few lncRNAs and miRNAs were recently linked to coronary heart disease and hypertension, the potential regulation of WNT3 and CAMK2N2 expression by ncRNAs in EH remains undefined." (PMID 32392180, 2020). "The present data adds to our understanding of the regulation of WNT/β-catenin signaling in hypertension, highlighting a novel mechanism by which LOC646616 binds miR-637 to relieve its inhibition on WNT3 expression." (PMID 32392180, 2020). "Importantly, our research also highlights a potentially critical role for the lncRNA LOC646616 in the activation of the WNT/β-catenin pathway by relieving the negative regulation exerted by miR-637 on both WNT3 and CAMK2N2 expression in human vascular smooth muscle cells during hypertension." (PMID 32392180, 2020). "Therefore, we propose that by releasing miR-637-mediated inhibition of both WNT3 and CAMK2N2 expression, LOC646616 upregulation in hypertension promotes WNT/β-catenin pathway activation both directly, through enhanced WNT3 expression, and indirectly, by preventing CAMKII-mediated inhibition." (PMID 32392180, 2020).
osteosarcoma (3 papers, 2021 to 2023). A usually aggressive malignant bone-forming mesenchymal neoplasm, predominantly affecting adolescents and young adults. "miR-376 c acts as a tumor suppressor in osteosarcoma by repressing proliferation, invasion, and differentiation via Wnt family member 3 (Wnt-3) and ARFGEF1 signaling pathways." (PMID 35048795, 2022).
ovarian carcinoma (3 papers, 2009 to 2024). A malignant neoplasm originating from the surface ovarian epithelium. "Likewise, the role of WNT3 and WNT8A in ovarian cancer needs to be further addressed." (PMID 19849863, 2009).
Anxiety (2 papers, 2016). Intense feelings of nervousness, tension, or panic often arise in response to interpersonal stresses. "We also investigated the role of Wnt2 and Wnt3 in anxiety-like behaviors." (PMID 27622936, 2016). "Thus, for both phenotypes, wnt3 mediated changes in this septal region may be related with anxiety and fear control: in Losers due to the defeat, and in Mirror-fighters due to the anxiety of an unsolved fight." (PMID 26909029, 2016).
apical periodontitis (2 papers, 2019 to 2024). "The polymorphic variations on the genes WNT3 and WNT3A were associated with increased susceptibility to apical periodontitis, specifically an intronic SNP in WNT3 (rs9890413) and a promoter SNP in WNT3A (rs1745420)." (PMID 31379856, 2019). "The WNT3 (rs9890413) SNP is in an intronic region and to this date has no known function, so its putative mechanism of action to regulate apical periodontitis susceptibility is indefinite." (PMID 31379856, 2019). "“SNPs in WNT3, WNT3A, WNT5A, WNT8A, WNT9B, and WNT11 genes” were examined to check their association with apical periodontitis." (PMID 39723289, 2024).
asthma (2 papers, 2023 to 2025). "Among these, we take two genes, WNT3 and HTR4, which are associated with mood swings with lung function, asthma, and COPD." (PMID 41295252, 2025). "Expression of WNT3, WNT5a, WNT10, and their receptor, Fzd-5, positively correlated with type 2-high asthma in adults whereas expression of WNT5b negatively correlated with type 2 inflammation." (PMID 37814791, 2023).
bladder urothelial carcinoma (2 papers, 2020 to 2022). "For example, SPAG5 promoted cell proliferation and reduced cell apoptosis in bladder urothelial carcinoma via regulating Wnt3/AKT/mTOR pathway." (PMID 35138218, 2022). "SPAG5 promotes proliferation and suppresses apoptosis in bladder urothelial carcinoma at least partially via up-regulating Wnt3 by activating the AKT/mTOR signaling pathway." (PMID 31985007, 2020).
celiac disease (2 papers, 2013 to 2021). An autoimmune genetic disorder with an unknown pattern of inheritance that primarily affects the digestive tract. "The locus rs2074404 of WNT3 was previously found to be a CD (Coeliac disease) associated polymorphism." (PMID 34868249, 2021).
colorectal tumors (2 papers, 2019 to 2025). "In colorectal tumors, we identified a subpopulation of secretory lineage cells that express antimicrobial peptides and Wnt3 and resemble Paneth cells." (PMID 40221753, 2025). "However, complete knowledge of the expression pattern of Wnt3 in CRC tissues and cell lines and molecular mechanism of its role in CRC tumorigenesis are undefined yet, although Voloshanenko and colleagues have documented an elevation of Wnt3 in colorectal tumors." (PMID 31632267, 2019).
diabetes (2 papers, 2015 to 2021). "Altogether, it is suggested that physical exercise in diabetes may promote neurogenesis through the activation of Wnt3 and Wnt signaling even though the role of Wnt3 in exercise-induced increases in neurogenesis in diabetes has not been studied yet." (PMID 26075247, 2015).
follicular thyroid carcinoma (2 papers, 2025). "Furthermore, research has shown that PMAIP1 influences the development of follicular thyroid carcinoma through the Wnt3/FOSL1 signaling pathway." (PMID 41323776, 2025).
liver fibrosis (2 papers, 2017 to 2022). "Our study found that the expression of Wnt genes (Wnt1, Wnt2, Wnt3, Wnt3a and Wnt5a) was upregulated, and Wnt pathway signalling in hepatocytes was active during the progression of schistosomiasis-induced liver fibrosis." (PMID 28331224, 2017). "Therefore, BMSCs might effectively inhibit liver fibrosis through Wnt3/β-catenin signalling in HSC-T6 cells." (PMID 35440002, 2022).
lung disease (2 papers, 2018 to 2025). "WNT3 is a critical gene associated with both psychotic disorders and lung diseases, influencing the WNT/β-catenin pathway vital for neural development and lung tissue maintenance." (PMID 41295252, 2025). "While there is substantial interest in Wnt signaling in lung disease, the contribution of WNT3 to the pathogenesis of COPD requires further investigation." (PMID 29566699, 2018).